NR5A1 (nuclear receptor subfamily 5 group A member 1)
Diseases named in the same sentence as NR5A1 in open-access papers (continued):
Sharing a sentence is not in itself a finding about the gene and the disease.
tumor (continued). "We have demonstrated that NR5A1 overexpression in ACC cells regulates the expression of both positive and negative dosage-dependent target genes which are directly implicated in shaping the malignant tumour phenotype." (PMID 38155952, 2023). "We observed that SF-1 and P450scc are co-expressed in PA cells of MENX-affected animals, and both siRNA-mediated silencing of the Nr5a1 gene and treatment with the SF-1 inhibitor IsoQ resulted in the down-regulation of Cyp11a1 in rat primary tumor cells and in LβT2 gonadotroph cells." (PMID 23756599, 2013). "We found that CX3CR1+ macrophages enhanced the expression of the corresponding target tumor inhibitory genes, such as BTG2, EGR2, ERG3, NR0B1, and SDC4, on NR5A1+ tumor cells." (PMID 38658971, 2024). "TAM subtypes interact with different PitNET lineages; CX3CR1+ TAMs interact with NR5A1+ tumor cells through the INHBA-ACVR1B axis, promoting tumor cell apoptosis." (PMID 38658971, 2024). "To investigate the regulatory role of CX3CR1+ macrophages on NR5A1+ tumor cells, we co-cultured PitNETs isolated CX3CR1+ or CX3CR1− macrophages with autologous CD45− tumor cells." (PMID 38658971, 2024). "Despite the tumor cells which were annotated based on lineage-specific transcription factors, namely POU1F1+, TBX19+, and NR5A1+ tumor cells, every cell type appeared across the three lineages." (PMID 38658971, 2024). "The results demonstrated that CX3CR1+, C1Q+, and GPNMB+ macrophages exhibited the highest interaction with NR5A1+, TBX19+, and POU1F1+ tumor cells, respectively." (PMID 38658971, 2024). "Particularly, the G1 and G1/S transition expression profiles differentiates better the NR5A1 from the POU1F1 and TBX19 tumor lineages, supporting the observation of the cyclins and CDK expression where CNFPA present more proliferation than the other tumors." (PMID 35260162, 2022). "TCF21 binds directly in the E-box promoter sequence of steroidogenic factor 1 (SF1/NR5A1), decreasing SF-1 transcription in both the human ACC cell line (H295R) and in ACC cell culture obtained from patient tumor fragment (ACC-T36)." (PMID 33729392, 2021). "The significant difference observed in the frequency of appreciable methylation (2nd quartile or higher) between tumor and normal ovarian tissue suggests that NR5A1 methylation is much more prevalent in tumors." (PMID 23291911, 2013). "This immune gene signature segregates along each tumor lineage and the transcription factor that determines their terminal differentiation: POU1F1-dependent GH-, TSH-, PRL-secreting PitNET; NR5A-1-driven gonadotrophinomas; and TBX19-dependent ACTH-secreting PitNET." (PMID 38790160, 2024). "Interestingly, genetic and epigenetic NR5A1 alterations do not correlate with markers of tumor progression (grade/stage) or survival." (PMID 23291911, 2013). "A small number of cells co-expressing NR5A1 and POU1F1 was observed in gonadotroph tumors (localized within the SF-1 gonadotroph cell cluster), as well as in two somatotroph tumor subtypes lacking NR5A1 expression (where these double-positive cells clustered within the PIT-1 cluster)." (PMID 40813692, 2025).
cancer (13 papers, 2013 to 2025). A tumor composed of atypical neoplastic, often pleomorphic cells that invade other tissues. "Together, our findings add a new layer of information to the previous understanding of how NR5A1 functions in steroidogenesis, reproductive organ differentiation, and even cancer development." (PMID 32093223, 2020). "Although NR5A1 has numerous functions including sex determination, adrenal development, and steroidogenesis, it is also involved in cancer development." (PMID 32093223, 2020). "Furthermore, the correlation between NR5A1 gene expression and ADS is even stronger when SW-13, the small cell cancer cell line, is excluded, suggesting the importance of NR5A1 as a master transcription factor in adrenocortical differentiation." (PMID 39162009, 2024). "NR5A1 is an orphan nuclear receptor which is proved to be essential for sexual differentiation and development of multiple endocrine organs, as well as the proliferation of cancer cells." (PMID 37564213, 2023). "While the role of NR5A1 in regulation of the expression of genes involved in steroid hormone synthesis and cellular cholesterol homeostasis pathways is well defined, little is known about how this nuclear factor contributes to the development of cancer." (PMID 35127484, 2021). "These evidence indicates that post-translational modifications such as phosphorylation and SUMOylation of NR5A1 may affect NR5A1 function in cancer cells." (PMID 32093223, 2020). "Therefore, cancer screening may be needed for patients with 46,XY GD who harbor DHX37 or NR5A1 variants." (PMID 40290305, 2025). "A total of 60 CRC TFs were obtained, among which SMAD3 were present in five types of common malignant tumors, while 46 CRC TFs including NR5A1 were only present in one type of malignant tumor." (PMID 34722892, 2021). "Crosstalk between NR5A1 and transforming growth factor (TGF) β signaling, Wnt/β-catenin signaling as well as cell proliferation and macromolecule synthesis pathways including glycolysis, have been proposed to contribute to cancer progression." (PMID 35127484, 2021). "Since both NR5A1 and ATF3 can regulate and cooperate with several transcription factors, we hypothesized that NR5A1 may interact with ATF3 and plays a functional role in cancer development." (PMID 32093223, 2020). "Taken together, these results support a novel relationship between NR5A1 and ATF3 and this relationship may have an impact in organ differentiation and cancer development." (PMID 32093223, 2020). "Steroidogenic Factor 1 (SF-1/NR5A1), an orphan nuclear receptor, is important for sexual differentiation and the development of multiple endocrine organs, as well as cell proliferation in cancer cells." (PMID 32093223, 2020). "The absence of correlation between the presence of somatic NR5A1 gene alteration and disease treatment (radiation/chemotherapy) suggests that these somatic events are not the result of cancer treatment." (PMID 23291911, 2013).
infection (4 papers, 2006 to 2025). The state of being infected such as from the introduction of a foreign agent such as serum, vaccine, antigenic substance or organism. "Infections of long-term cultures of differentiating bovine theca cells (days 5, 8, and 11 of culture) were performed in order to analyze the effects of NR5A1 wild-type and mutant over-expression." (PMID 17176485, 2006). "The presentation of the normalized results of the infection experiments levels out the stimulation or inhibition of expression by LH, displaying solely the transcriptional effects of NR5A1 over-expression." (PMID 17176485, 2006). "Moreover, we ascertained that the rise in RAB-10 activity, due to infection, was attributed to the augmented expression of LET-413/Erbin, and the nuclear receptor NHR-25/NR5A1/2 was determined to be indispensable for this increase." (PMID 39087719, 2025). "The results show that previous infection and over-expression of wild-type or mutant NR5A1 did not influence the acute cellular response of bovine theca cells to the luteinizing stimulus." (PMID 17176485, 2006). "The results of the initial experiments demonstrate that infection with recombinant adenoviruses at a multiplicity of infection of 100 induces expression of wild-type and mutant NR5A1 to high levels in bovine theca cells without toxic effects and without disturbing intracellular responses." (PMID 17176485, 2006).
metabolic disorders (2 papers, 2022 to 2024). "NR5A1, one of the important genes of glycolysis regulation and control, is significantly upregulated to correct energy metabolic disorders and maintain the normal energy metabolism in the intervertebral disc." (PMID 36267810, 2022).
benign tumors (1 paper, 2013). "Examination of larger numbers of non-advanced and/or benign tumors for somatic NR5A1 alterations, may help confirming this concept." (PMID 23291911, 2013).
hematological cancers (1 paper, 2021). "Only one other study has linked NR5A1 to hematological cancers; a recent large NGS short hairpin RNA knockdown screen identified NR5A1 as a crucial gene for leukemic cell survival in one out of six primary AML samples, but the significance of this finding remains unclear." (PMID 35127484, 2021).
NR5A1 also shares sentences with these, for which no sentence is quoted: IMAGe syndrome (4 papers); adrenal tumors (3); depression (3); X-linked adrenal hypoplasia congenita (3); adrenal hyperplasia (2); Adrenal hypoplasia congenita (2); androgen excess (2); gonadotroph adenomas (2); Hypoglycemia (2); MIRAGE syndrome (2); oligospermia (2); 3-beta hydroxysteroid dehydrogenase deficiency (1); Abdominal obesity (1); Achalasia-Addisonianism-Alacrima syndrome (1); adrenal adenoma (1); adrenal cancer (1); age (1); amenorrhea (1); asplenia (1); Ataxia (1); breast carcinoma (1); cervical carcinoma (1); cholestasis (1); complete androgen insensitivity syndrome (1); Congenital adrenal hypoplasia (1); corticotroph adenomas (1); Cushing syndrome (1); cystic fibrosis (1); dementia (1); Duchenne muscular dystrophy (1).
A further 28 diseases each share a sentence with NR5A1 in 1 paper.